MIR6807 (microRNA 6807)
Synonyms: hsa-mir-6807
Gene: MicroRNA gene on chromosome 19 (58,550,285 to 58,550,376, forward strand). Ensembl gene ENSG00000275924.
Homologues: Orthologues: chimpanzee MIR6807 (100% identical).